BRCA1 (BRCA1 DNA repair associated)
Diseases named in the same sentence as BRCA1 in open-access papers (continued):
Sharing a sentence is not in itself a finding about the gene and the disease.
breast cancer (continued). "The female population with BRCA1/2 mutations has several options to prevent developing breast cancer, including surgery, medication, and lifestyle." (PMID 37476378, 2023). "In the present study, we found 3 out of 12 patients (25%) with BRCA1/2 mutations had bilateral breast cancer (one with metachronous bilateral breast cancer and two with synchronous bilateral breast cancer)." (PMID 35778884, 2023). "In summary, this study has identified a novel mechanism to promote BRCA1-deficiency in breast cancer cells." (PMID 37298108, 2023). "A mutation in the genes breast-cancer-1 (BRCA1) or breast-cancer-2 (BRCA2) is carried by 25% of patients with familial predisposition." (PMID 36765786, 2023). "The increase in DNA damage associated with breast cancer patients who harbour the BRCA1/2 mutation occurs via a process known as synthetic lethality." (PMID 38263984, 2023). "Some studies have found that the majority (80%) of breast cancer cases expressing the BRCA1 hereditary mutated form can be classified as triple-negative breast cancers (TNBC) and/or basal-like breast cancers (BLBC), of which TNBCs represent 15% to 20%." (PMID 37296801, 2023). "In China, the prevalence of BRCA1/2 in high‐risk patients is 9.1%, but only 3.5% in sporadic breast cancer patients." (PMID 35778884, 2023). "For breast cancer, the lifetime risk is roughly five to seven times higher for BRCA1/2 pathogenic variant carriers compared to women in the general population." (PMID 37185387, 2023). "Olaparib was the first poly(ADP-ribose) polymerase (PARP) inhibitor to be approved for the treatment of advanced breast cancers with BRCA1/2-inherited mutations and represents the first targeted-therapy approved for TNBC2." (PMID 37582853, 2023). "Certain genomic mutations such as BRCA2 and BRCA1 participate in breast cancer development (Yoshimura, Imoto & Iwata, 2022)." (PMID 37426414, 2023). "A previous breast cancer study from Bashkortostan identified c.5266dupC in some 4% of breast cancer patients, indicating a three– to fourfold enrichment of pathogenic BRCA1 variants in ovarian cancer compared to breast cancer from the same population." (PMID 37013556, 2023). "Traditionally, genetic testing for breast cancer has been restricted to high-risk predisposition genes, such as BRCA1 and BRCA2." (PMID 37656691, 2023). "We further demonstrate that rare missense variants in BRCA1 were associated with an increased risk of breast cancer overall." (PMID 37790698, 2023). "Magnetic resonance imaging (MRI) represents the most sensitive technique to detect breast cancer, and this is recommended annually in addition to mammography for screening women with an inherited BRCA1 or BRCA2 mutation." (PMID 37370892, 2023). "In Japan, 1.45% of breast cancer cases reportedly involve a BRCA1 pathogenic variant and 2.71% have some BRCA2 pathogenic variant." (PMID 37957733, 2023). "Individuals with germline mutations in the BRCA1/2 genes are at a higher risk in developing various types of cancers, including cancers of the breast, ovary, pancreas, and prostate." (PMID 37035242, 2023). "The increase of only SBS13 mutations in BRCA1/2-deficient breast cancers mirrors our observation that increased APOBEC-induced mutation is driven by higher rates of C-to-G substitutions in recombination-deficient yeast strains." (PMID 37532520, 2023).
breast cancer (continued). "A previous meta-analysis reported that the risk of breast cancer was reduced by about 50% in carriers of BRCA1 and BRCA2 mutations who underwent risk-reducing bilateral salpingo-oophorectomy (RRSO)." (PMID 37781206, 2023). "Individuals carrying BRCA1 or BRCA2 mutations have a higher lifetime risk of developing breast cancer and an increased risk of ovarian cancer." (PMID 37575755, 2023). "Screening for germline pathogenic BRCA1 or BRCA2 variants (gBRCA) in high-risk breast cancer patients is known to be cost-effective in high-income countries." (PMID 38162618, 2023). "Women who carry pathogenic BRCA1 variants are particularly likely to develop breast cancer (BC) and ovarian cancer (OC), with a 45–79% and 39–48% chance, respectively." (PMID 37958491, 2023). "In BRCA1 mutated breast cancer cells, the loss of 53BP1 rescues the BRCA1 deficiency and prevents genomic instability by activating the ATM-mediated processing of broken DNA ends." (PMID 37892162, 2023). "This is the first study with a large prospective component to analyze the association anthropometric measures with breast cancer risk by menopausal status for BRCA1 and BRCA2 variant carriers separately." (PMID 37340476, 2023). "Hereditary mutations in BRCA1 predispose carriers to breast cancer, and spontaneous breast cancers often exhibit defects in BRCA1 expression." (PMID 37627161, 2023). "Women face an approximately 72 and 69% risk of developing breast cancer associated with BRCA1 and BRCA2 mutations, respectively, by the age of 80, compared with 12% among women in the general population." (PMID 36690978, 2023). "In particular, BRCA1/2, breast cancer-associated genes 1 and 2, are the most well-known tumor suppressors in breast cancer." (PMID 36810560, 2023). "In case of breast cancer in a patient with BRCA1/2 mutation, for example, for the contralateral reconstruction after prophylactic mastectomy, the technique depends on the possibility of post-operative radiation therapy." (PMID 36401760, 2023). "A large prospective study found that women who inherit deleterious germline mutations of BRCA1 or BRCA2 have very high cumulative risks for developing breast cancer (e.g., risks to 80‐year‐olds are 72% and 69% for BRCA1 and BRCA2 carriers, respectively)." (PMID 35778884, 2023). "Although prophylactic surgery reduces the risk of mammary neoplasm in BRCA1/BRCA2 mutation carriers, it has drawbacks related to early menopause." (PMID 36835955, 2023). "Ovarian cancer and breast cancer are hereditary cancers, and BRCA1 and BRCA2 are well known as causative genes." (PMID 37781206, 2023). "In other ethnic groups, a relatively high rate of BRCA1/2 germline variants was reported in familial breast cancer in Turkey (9.1%), and in Chinese patients with hereditary breast/ovarian cancer (9.4%)." (PMID 37656691, 2023). "On the contrary, HER2-low breast cancer had a higher proportion of HG and NG 2 tumors, and, although the percentage was small, a higher detection rate of BRCA1/2 mutations compared to HER2-0 breast cancer." (PMID 38001620, 2023). "Researchers have been committed to investigate effective neoadjuvant chemotherapy strategies at the molecular level, with a focus on genetic background of breast-cancer susceptibility genes such as BRCA1/2 loss-of-function mutations." (PMID 37813891, 2023). "Three of our BRCA1 mutation carriers also had breast cancer (and one additional cervical cancer), and one MSH6 mutation carrier also had endometrial cancer, in line with the known role of these genes in different types of DNA repair and cancer predisposition." (PMID 37013556, 2023). "Our result is consistent with their finding that the frequency of P/LP variants in genes susceptible to breast cancer is 4.7% in BRCA1/2-negative candidates." (PMID 36647026, 2023). "They identified 13/23 (56.5%) with a BRCA1 pathogenic variant compared to 11.5% (597/5,203) with other breast cancer types (p < 0.0001)." (PMID 37592173, 2023).
breast cancer (continued). "Women with BRCA mutation (BRCA1 or BRCA2) have a substantially 69–72% increased risk of developing breast cancer." (PMID 37406000, 2023). "In this study, we found that women at high risk of developing breast cancer due to an inherited BRCA1 or BRCA2 mutation who used vitamin D supplements had 46% lower odds of having breast cancer." (PMID 37345127, 2023). "This suggested that the expression of ABCG2/CD338 proteins was specific to the tumor-initiating luminal progenitor subpopulation of BRCA1-mutated breast cancer cells." (PMID 36834918, 2023). "Consistent with TNBC, breast cancer patients who carried BRCA1-deficient is sensitive to DNA damage drugs such as platinum." (PMID 36906594, 2023). "Two biological explanations for our findings of high baseline BMI and of weight change and higher breast cancer risk in the postmenopausal cohort of carriers of BRCA1 can be considered." (PMID 37340476, 2023). "Approximately 10% of breast cancer cases occur in patients with germline pathogenic variants of BRCA1, BRCA2, and other DDR genes, which are correlated with an increased risk of breast, and other cancers." (PMID 37350936, 2023). "Another study found that 2.5% of unselected breast cancer patients carry pathogenic BRCA1/2 variants." (PMID 37958491, 2023). "The tumor suppressors breast cancer susceptibility genes BRCA1 and BRCA2 are critical to the repair of double-strand breaks in DNA via homologous recombination repair (HRR)." (PMID 37803017, 2023). "TNBC makes up between 1 -24% of all cases of breast cancer and it mainly affects younger patients and those who have the breast cancer gene 1 (BRCA1) mutation." (PMID 36883091, 2023). "Comprehensive genomic profiling revealed that a subset of breast carcinomas with an HRR gene mutation other than BRCA1/2 had a low LOH score." (PMID 37173992, 2023). "Family history is a recognized significant risk factor for breast cancer (BC), with hereditary susceptibility attributed to mutations in genes like BRCA1 and BRCA2." (PMID 37888069, 2023). "Breast cancer (BC) is the most prevalent malignancy among women worldwide with germline pathogenic variants/likely pathogenic variants (PVs/LPVs) in BRCA1/2 accounting for a large portion of hereditary cases." (PMID 38017116, 2023). "Germline inactivating mutations in the BRCA1 gene lead to an increased lifetime risk of ovarian and breast cancer (BC)." (PMID 37373065, 2023). "The study revealed that beta hCG expression is related to the BRCA1 status, with overexpression observed in cases of breast carcinoma with BRCA1 mutation." (PMID 37580469, 2023). "Approximately 10% of breast cancer (BC) cases are hereditary, and germline pathogenic variants in BRCA1 and BRCA2 genes account for 20% of familial BC cases." (PMID 38067403, 2023). "An ensemble approach (EnsembleFit), which leverages output from all five tools, increased SBS3 assignment accuracy in BRCA1/2-deficient breast carcinomas." (PMID 37742051, 2023). "Young age at breast cancer (BC) diagnosis and family history of BC are strongly associated with high prevalence of pathogenic variants (PVs) in BRCA1 and BRCA2 genes." (PMID 37084156, 2023). "A previous study showed that the probability of breast cancer in BRCA1 mutation carriers is 57–65%, while the probability of breast cancer in BRCA2 mutation carriers is 45–49%." (PMID 35409110, 2022).
breast cancer (continued). "The hereditary component of premenopausal breast cancer is further illustrated by the considerably higher BRCA1/2 mutation prevalence in families with a history of breast cancer and premenopausal female members affected by the disease." (PMID 36011273, 2022). "Carriers of the BRCA1/BRCA2 mutation are estimated to have a 10-fold higher risk of developing breast cancer." (PMID 35626173, 2022). "In our study, CNV deletions overlapping SULT1A1 were identified in 1.7% of BRCA1 pathogenic variant carriers and they suggested a decreased breast cancer HR (HR = 0.73, 95%CI = 0.59–0.91, p = 9.1 × 10−3)." (PMID 36203093, 2022). "The PARP inhibitor olaparib has a more obvious effect on patients with BRCA1 deficiency in the treatment of breast cancer, but patients with BRCA1 deficiency account for only a part of the population." (PMID 35563196, 2022). "Hereditary breast cancers account for 5–10% of all breast cancers, and the most common causes of the disease are mutations in the BRCA1/BRCA2 genes." (PMID 36057718, 2022). "In the mutation driver module for breast cancer, both BRCA1 and BRCA2 are exactly connected to PARP1." (PMID 36266635, 2022). "Risk-reducing mastectomy (RRM) nearly eliminates breast cancer risk in female BRCA1/2 carriers and is routinely discussed." (PMID 36548287, 2022). "Germline mutations of BRCA1 have been found to contribute to approximately 25%–40% of all familial breast cancer cases and most familial ovarian cancer cases." (PMID 35025764, 2022). "Some risk factors are constant, such as age and mutations in the BRCA1 and BRCA2 genes, which are estimated to account for 20% to 40% of inherited breast cancers with harmful mutations in BRCA1 and BRCA2." (PMID 35663041, 2022). "Previous studies have shown that people who carry the breast cancer susceptibility gene 1 (BRCA1) or breast cancer susceptibility gene 2 (BRCA2) variants are predisposed to breast cancer." (PMID 36540803, 2022). "The PRSER+ yielded the strongest associations with overall breast cancer risk for BRCA1 (OR = 1.40, 95% CI = 1.07 to 1.83) and BRCA2 (OR = 1.33, 95% CI = 1.16 to 1.52) carriers." (PMID 34320204, 2022). "The PARP inhibitor Olaparib is the first drug to be clinically used in treating breast cancer patients with BRCA1/2 mutation based on the SL interaction mechanism." (PMID 35918352, 2022). "One model (PredictCBC-1A) was developed including information about BRCA1/2 mutation status and another model (PredictCBC-1B) for the general breast cancer population of genetically untested women." (PMID 36271417, 2022). "In the initial step of this mechanism, unsynapsed chromosome axes (XY axes in MSCI) are recognized by BRCA1, the protein product of breast cancer susceptibility gene 113,40,41, by the ATR activator TOPBP122,24,42, and by ATR." (PMID 36443288, 2022). "Later, it was suggested that combining these factors by calculating the mean score of the three indices robustly predicted BRCA1/2 deficiency in breast cancer." (PMID 35163621, 2022). "Among 91 patients with HER-2-negative advanced or relapsed breast cancer, including 2 men and 89 women, 8 were diagnosed with pathogenic or likely pathogenic variants: BRCA1 (n = 4) and BRCA2 (n = 4)." (PMID 35627717, 2022). "These hereditary breast cancers, a large part about 80-90% cases, are related to germ line mutations within the BRCA1, BRCA2, and MDR1 gene." (PMID 35837379, 2022). "Some studies suggest that breast cancer BRCA1/2 mutation carriers have poorer overall survival (OS)." (PMID 35409110, 2022). "Although the BD-L signature was present in all breast cancer subtypes, it was significantly higher in BRCA1-mutated primary tumors than in sporadic breast tumors." (PMID 36612206, 2022).
breast cancer (continued). "Here, we have conducted the largest and most comprehensive genome-wide association study of CNVs and breast cancer risk for BRCA1 and BRCA2 pathogenic variant carriers." (PMID 36203093, 2022). "Significant associations emerged between the intention to uptake BRCA1/2 genetic testing and age, parental status, breast cancer risk perception, self-referred outcome expectancies, perceived benefit, coping self-efficacy, and planning." (PMID 35448177, 2022). "Significant associations emerged between the intention to undergo BRCA1/2 genetic testing and age, parental status, breast cancer risk perception, self-referred outcome expectancies, perceived benefit, coping self-efficacy, and planning." (PMID 35448177, 2022). "These defects in DDR machinery result in the loss of function for genes implicated in DNA repair (i.e., breast cancer susceptibility gene 1/2—BRCA1/BRCA2) or dysregulation of cell cycle phases." (PMID 35954325, 2022). "BRCA1/2 mutation carriers in the BROV probands had a stronger family history of breast cancer than the OV probands (p value = .040)." (PMID 35608067, 2022). "BRCA1 can repair double-stranded DNA damage to maintain genomic stability, and BRCA1 mutations increase the risk of breast cancer." (PMID 36118853, 2022). "CNV loci suggested to modify breast cancer risk estimates in BRCA1/2 pathogenic variant carriers, were examined to identify a candidate gene for functional characterisation using in silico and in vitro assays." (PMID 36203093, 2022). "PRSBC and PRSER+ were associated with larger odds ratio estimates than PRSER- in predicting breast cancer risk, consistent with the fact that most breast cancers in men are ER positive, including those harboring BRCA1 and BRCA2 pathogenic variants." (PMID 34320204, 2022). "Exon 11 of the BRCA1 gene is the site for frequent mutations in breast cancer individuals and has been reported among breast cancer patients in Africa including populations from Nigeria, Egypt, Tunisia, Morocco, Algeria and South Africa." (PMID 36942145, 2022). "Poly-adenosine diphosphate ribose polymerase (PARP) inhibitors (PARPi) are approved for BRCA1/2 carriers with HER2-negative breast cancer in the adjuvant setting with a high risk of recurrence as well as the metastatic setting." (PMID 36077867, 2022). "Lurbinectedin, a selective inhibitor of oncogenic transcription, has shown preclinical antitumor activity against homologous recombination repair-deficient models and preliminary clinical activity in BRCA1/2 breast cancer." (PMID 36037567, 2022). "Previous studies have revealed that BRCA1 mutation contributes to breast cancer development by creating a pro-tumorigenic niche and affects the transformation of CAFs to metastasis associated fibroblasts (MAFs)." (PMID 35626017, 2022). "Mutations in BRCA1 gene were associated with shorter survival in breast cancer, but longer survival in ovarian and endometrial cancers." (PMID 35444210, 2022). "While evaluation of BRCA1 has been so closely associated with breast cancer (the initials stemming from the words BReast CAncer point to that directly)!" (PMID 35047126, 2022). "This is unexpected as LPs have been implicated as the driver in the onset of BRCA1 mutation associated breast cancer." (PMID 35118379, 2022). "In a meta-analysis deliberated beforehand, which studied COC use among BRCA1/2 mutation carriers, relationships between ever-use of oral contraceptives and ovarian and breast cancer among women who are carriers are akin to those shown for the common populace." (PMID 36072240, 2022). "For the breast cancer with BRCA1 and BRCA2 mutations, there is a strong association with an increased risk for a second breast or ovarian cancer." (PMID 35281878, 2022).